NEUROD6 (neuronal differentiation 6)
Description:
Activates E box-dependent transcription in collaboration with TCF3/E47. May be a trans-acting factor involved in the development and maintenance of the mammalian nervous system. Transactivates the promoter of its own gene (By similarity).
Synonyms: bHLHa2; ATOH2; NEX1M; Math-2; Nex1; MATH2
Tractability: PROTAC: ubiquitination databases record sites on it.
Gene: Protein-coding gene on chromosome 7 (31,337,465 to 31,340,726, reverse strand). Ensembl gene ENSG00000164600.
Subcellular location: Nucleus
Gene Ontology:
Molecular function: DNA-binding transcription factor activity, RNA polymerase II-specific; E-box binding; DNA-binding transcription activator activity, RNA polymerase II-specific; protein dimerization activity; RNA polymerase II cis-regulatory region sequence-specific DNA binding
Biological process: axon development; positive regulation of transcription by RNA polymerase II; sensory organ development; nervous system development; regulation of DNA-templated transcription
Cellular component: chromatin; nucleus
Genetic constraint (gnomAD): Loss-of-function variants: 5 observed, 25.47 expected, observed/expected ratio (o/e) 0.2, 90% interval 0.1 to 0.41. The upper end of that interval is the gene's LOEUF score, 0.41, which puts it in group 1 of 6, group 1 being the genes least tolerant of losing a copy. Missense variants: 325 observed, 431.84 expected, observed/expected ratio (o/e) 0.75, 90% interval 0.69 to 0.82. Synonymous variants: 182 observed, 162.63 expected, observed/expected ratio (o/e) 1.12, 90% interval 0.99 to 1.26.
Homologues: Orthologues: chimpanzee NEUROD6 (100% identical), dog NEUROD6 (100% identical), macaque NEUROD6 (100% identical), pig NEUROD6 (100% identical), guinea pig NEUROD6 (99% identical), rat Neurod6 (99% identical), mouse Neurod6 (98% identical), tropical clawed frog neurod6 (85% identical), zebrafish neurod6a (64% identical), zebrafish neurod6b (59% identical), Drosophila melanogaster tap (19% identical), Caenorhabditis elegans ngn-1 (18% identical), and 3 more. Paralogues in human: NEUROD1 (49% identical), NEUROD2 (49% identical), NEUROD4 (42% identical), NEUROG2 (22% identical), NEUROG1 (21% identical), ATOH1 (19% identical), NEUROG3 (18% identical), BHLHE22 (16% identical), BHLHA15 (16% identical), BHLHE23 (16% identical), OLIG3 (16% identical), OLIG2 (16% identical), and 3 more.
Diseases named in the same sentence as NEUROD6 in open-access papers:
NEUROD6 is named in the same sentence as 21 diseases in open-access papers, as found by Europe PMC text mining. Sharing a sentence is not in itself a finding about the gene and the disease. The quoted sentences say what the papers report.
Alzheimer disease (4 papers, 2014 to 2022). A progressive, neurodegenerative disease characterized by loss of function and death of nerve cells in several areas of the brain leading to loss of cognitive function such as memory and language. "Recently, NEUROD6 was revealed as a potential biomarker for of Alzheimer’s disease (AD) diagnosis." (PMID 36313022, 2022). "C-Met, NPTX2, NEUROD6, and hyperpolarization-activated cyclic nucleotide-gated potassium channel 1 have all been found to be HCN1 in a study comparing gene expression in Alzheimer's and nondisordered Alzheimer's diseases." (PMID 35310907, 2022).
Parkinson disease (4 papers, 2018 to 2022). A progressive degenerative disorder of the central nervous system characterized by loss of dopamine producing neurons in the substantia nigra and the presence of Lewy bodies in the substantia nigra and locus coeruleus. "NeuroD6-expressing DA neurons were recently identified as neuroprotected in experimental Parkinsons." (PMID 31097625, 2019). "NEUROD6 may also improve cellular resistance to oxidative stress, which is important in neurodegenerative illness prevention including Parkinson’s disease and autism spectrum disorder." (PMID 36313022, 2022). "Grp-/Neurod6+ dopamine neurons represent a smaller VTA subpopulation, which is preferentially spared in a 6-OHDA model of Parkinson’s disease." (PMID 30135866, 2018).
Anxiety (2 papers, 2019 to 2022). Intense feelings of nervousness, tension, or panic often arise in response to interpersonal stresses. "In the elevated plus maze task, we found that Tcf4STOP/+::Neurod6-Cre and control mice exhibited increased closed arm activity compared to Tcf4STOP/+ mice, showing that reinstating Tcf4 in glutamatergic neurons restored the low-anxiety phenotype." (PMID 35535852, 2022).
ependymoma (2 papers, 2020 to 2025). A WHO grade II, slow growing tumor of children and young adults, usually located intraventricularly. "Here the authors show that YAP1 activation in NeuroD6 positive neuronal precursor cells can induce ependymoma-like tumours in mice." (PMID 32404936, 2020).
schizophrenia (2 papers, 2025). A major psychotic disorder characterized by abnormalities in the perception or expression of reality. "In particular, genes associated with male-biased neurological diseases (e.g., NEUROD6 for autism, CNIH2 for schizophrenia) were differentially expressed between DHT- and nonresponded neurons but not between DHT and mock-treated neurons." (PMID 39622637, 2025).
anxiety disorder (1 paper, 2021). A category of psychiatric disorders which are characterized by anxious feelings or fear often accompanied by physical symptoms associated with anxiety. "Several DEGs shared by the male Tg and NTg have previously been linked to early-life stress, anxiety disorders and ADHD (Erbin), sex-specific gene expression in ASD and dopamine changes (Erbb2ip, Neurod6), and to TH-dependent growth and embryonic differentiation processes (Secisbp2l)." (PMID 34100083, 2021).
attention deficit-hyperactivity disorder (1 paper, 2018). A disorder characterized by a marked pattern of inattention and/or hyperactivity-impulsivity that is inconsistent with developmental level and clearly interferes with functioning in at least two settings (e.g. at home and at school). "Additionally, six genes displaying at least differential expression among hemispheres (BAIAP2, DAPPER1, LMO4, NEUROD6, ATP2B3, and ID2) in a case-control association study in an initial Spanish sample of ADHD (Attention Deficit Hyperactivity Disorder) patients and control subjects." (PMID 30081481, 2018).
brain tumour (1 paper, 2020). "Here we show that, ectopic expression of active nuclear YAP1 (nlsYAP5SA) in ventricular zone neural progenitor cells using conditionally-induced NEX/NeuroD6-Cre is sufficient to drive brain tumour formation in mice." (PMID 32404936, 2020).
cognitive decline (1 paper, 2025). "Therefore, the downregulation of VGF, NEUROD6, KCNF1, KCNE5, CRH, and RPH3A may contribute to the cognitive decline observed in elderly individuals with AD." (PMID 39834440, 2025).
epilepsy (1 paper, 2013). A brain disorder characterized by episodes of abnormally increased neuronal discharge resulting in transient episodes of sensory or motor neurological dysfunction, or psychic dysfunction. "NEUROD6, a gene responsible for granule cell differentiation in the hippocampus, was described as not expressed in heterotopic neurons in epilepsy-induced hippocampal heterotopia." (PMID 24278214, 2013).
neuroblastoma (1 paper, 2020). Neuroblastoma (NB) is the most common solid, extracranial childhood tumor. "BMP2 induced neural differentiation in mouse neuroblastoma cells by increasing the expression of neurogenic transcription factors Dlx2, Brn3a, and NeuroD6." (PMID 32210188, 2020). "Our transcriptomic analysis did not support activation of DLX2, BRN3A, or NEUROD6 genes as being involved in the BMP4-induced phenotypes of neuroblastoma cells, as previously suggested by studies using BMP2." (PMID 32210188, 2020).
pheochromocytoma (1 paper, 2014). "Constitutive expression of NeuroD6 triggers neuronal differentiation of PC12 cells, originated from a pheochromocytoma of the rat adrenal medulla, without requirement of nerve growth factor (NGF)." (PMID 25548427, 2014).
tumour (3 papers, 2020 to 2025). "In addition to the transcription factors that were found to be overexpressed, Neuronal Differentiation 6 (NEUROD6) exhibited a tumor-suppressive role in GPs via the inhibition of cell proliferation, migration, and tumor formation ability in GBM cell lines." (PMID 40143207, 2025).
neurodegenerative disease (2 papers, 2015 to 2022). A disorder of the central nervous system characterized by gradual and progressive loss of neural tissue and neurologic function. "Among these genes of neurodegenerative diseases, we observed that the NAP1L5 expression was significantly positively correlated with NEUROD6 and NRN1, whereas correlated with negatively CD163, ITPKB, and AQP1." (PMID 36568274, 2022).
psychiatric disease (2 papers, 2018 to 2023). "Together with previous studies on the NeuroD6 subpopulation, our findings pinpoint the importance of unraveling the molecular and functional role of VTA subpopulations in order to better understand normal behavior and psychiatric disease." (PMID 36825278, 2023). "Therefore, our identification of Neurod6 as a marker for this cell population enables future mechanistic investigations into how this DA subcircuit controls motivated behaviors, the dysfunction of which may be important for the pathophysiology of psychiatric disorders such as drug addiction." (PMID 30135866, 2018).
NEUROD6 also shares sentences with these, for which no sentence is quoted: atherosclerosis (1 paper); autism (1); autism spectrum disorder (1); cancer (1); cognitive deficits (1); neurological diseases (1).